SIRT6 (sirtuin 6)
Diseases named in the same sentence as SIRT6 in open-access papers (continued):
Sharing a sentence is not in itself a finding about the gene and the disease.
Obesity (continued). "Notably, the beneficial effects of chrysophanol on reducing FBG, GGT, and ITT were largely diminished in SIRT6 FKO obese mice, suggesting a critical role of SIRT6 in mediating the effects of chrysophanol in preventing obesity, improving glucose tolerance and insulin sensitivity." (PMID 33274005, 2020). "Sirt6-mediated regulation of microenvironmental conditions in WAT, such as type 2 cytokine IL-4 production by adipocytes, may play important roles in protecting against obesity and insulin resistance." (PMID 31113929, 2019). "Finally, we demonstrate that Sirt6 functions as a tumor suppressor in the liver, and consequently, deletion of Sirt6 in the liver leads to not only the spontaneous development of tumors but also enhanced tumorigenesis in response to DEN treatment or under conditions of obesity." (PMID 38332150, 2024).
atherosclerosis (59 papers, 2011 to 2025). A disease characterized by the build-up of fatty material and calcium deposition in the arterial wall resulting in partial or complete occlusion of the arterial lumen. "Innovative discoveries in the research revealed that atherosclerosis is caused by lipid metabolism disorders due to downregulated Sirt6 expression." (PMID 37736721, 2023). "Our findings illustrated that Sirt6 is implicated in the pathogenesis of atherosclerosis by promoting lipophagy and subsequently improves lipid metabolism disorder in macrophages." (PMID 37736721, 2023). "We aimed to investigate the role of hepatocyte SIRT6 in the development of atherosclerosis and further characterize the mechanism underlying SIRT6’s effect on NAFLD." (PMID 37566087, 2023). "In ApoE-/- mice fed a high-fat diet (HFD), endothelial loss of SIRT6 promotes monocyte adhesion to ECs, impairs endothelium-dependent vasorelaxation, and facilitates atherosclerosis development." (PMID 35855341, 2022). "Autophagy activation of macrophages caused by sirtuin 6 (Sirt6) overexpression can restrain apoptosis, reduce macrophage foam cell formation, and stabilize atherosclerosis plaques." (PMID 35096837, 2021). "SIRT6-knocked down and apolipoprotein E-deficient hypercholesterolemic mice tends to develop atherosclerosis by increasing inflammation in the endothelial cells." (PMID 34071497, 2021). "Our study indicates that endogenous levels of SIRT6 are a critical regulator of VSMC senescence which depend upon its catalytic activity, and suggest that loss of SIRT6 activity is an important factor in VSMC senescence in atherosclerosis." (PMID 33353368, 2021). "SIRT6 has not only been reported to protect against liver fibrosis, atherosclerosis, osteoarthritis, and arthritis but has also been associated with increased TNF production and the development of autoimmune encephalomyelitis and cerebral ischemia." (PMID 28894448, 2017). "In this report, we aim to address the role of SIRT6 in regulating endothelial dysfunction and atherosclerosis in mice and explore the underlying molecular mechanisms." (PMID 27249230, 2016). "The function of SIRT6 on various physiological and pathological processes has been widely studied, and SIRT6 deficiency or dysregulation is closely associated with diverse human diseases including cardiac hypertrophy, adipocyte disorders, and atherosclerosis." (PMID 27118880, 2016). "However, its pernicious effect also warrants further inquiry, and more experiments are required to inspect the underlying mechanism(s) or the exact molecule(s) by which Sirt6 exerts a regulatory effect on the pathogenesis of atherosclerosis." (PMID 37497437, 2023). "Additionally, the expression of tumor necrosis factor superfamily member 4 (TNFSF4, also known as OX40 L), a risk factor for atherosclerosis, was reduced by SIRT6 under normal conditions or after TNF-α stimulation." (PMID 36465178, 2022). "Also, the abnormal expression of endothelial inflammatory factors regulated by SIRT6 is implicated in the formation of atherosclerosis." (PMID 33855020, 2021). "Decreased expression of Sirt6 is a widely accepted risk factor of DM and atherosclerosis." (PMID 29371988, 2017). "Whether Sirt6 is involved in atherosclerosis development, the major cause of cardiovascular diseases, is unknown." (PMID 27045575, 2016). "Knockout of SIRT6 caused elevated serum cholesterol levels, while ectopic expression of SIRT6 diminished the serum cholesterol levels, thus improving hypercholesterolemia and atherosclerosis." (PMID 27118880, 2016). "It should be emphasized that although we and other researchers have arrived at the same conclusion that SIRT6 suppression may underscore the pathogenesis of atherosclerosis and, more broadly, coronary heart disease, the underlying mechanism may not entirely rely on MRTF-A." (PMID 35246513, 2022).
atherosclerosis (continued). "Previous studies have highlighted the importance of SIRT6 in protecting blood vessels and the heart from endothelial dysfunction, atherosclerosis, myocardial fibrosis, and ischemia or reperfusion injury." (PMID 39851250, 2025). "In line with this, SIRT6 was shown to decrease the expression of atherosclerosis‐inducing factors such as TNFSF4 (tumor necrosis factor superfamily member 4), by deacetylating H3K9 at their promoter." (PMID 39215785, 2025). "Specifically, SIRT6 has a protective role against atherosclerosis by preventing DNA damage, inhibiting apoptosis and inflammatory response, finally inhibiting the senescence of VSMCs." (PMID 39215785, 2025). "Together, these results indicated that Sirt6 influences endothelial cell function to a large extent and affects atherosclerosis development." (PMID 37497437, 2023). "Hepatocyte SIRT6 also likely inhibited the development of atherosclerosis by inhibiting intestinal lipid absorption and hepatic VLDL secretion." (PMID 37566087, 2023). "Previous studies have shown that the expression of SIRT6 was reduced in human and mouse VSMCs in plaques, and smooth muscle-specific overexpression of SIRT6 attenuated the development of atherosclerosis." (PMID 37607939, 2023). "In conclusion, we revealed that smooth muscle LKB1 inhibits VSMC-derived foam cell formation and atherosclerosis via direct phosphorylation and activation of SIRT6 and subsequent inhibition of LOX-1 expression." (PMID 37607939, 2023). "Recent studies demonstrated various involvements of Sirt6 in endothelial dysfunction whose occurrence contributes to atherosclerosis progression." (PMID 37497437, 2023). "Recently, literature suggested that Sirt6 counters against atherosclerosis through alleviating fatty acid infiltration in the liver in hypercholesterolemic transgenic mice." (PMID 37497437, 2023). "Sirt6 also plays significant roles in regulating several cardiovascular diseases including atherosclerosis, coronary heart disease, as well as cardiac remodeling, bringing Sirt6 into the focus of clinical interests." (PMID 37497437, 2023). "For instance, Sirt6 inhibits mouse vascular endothelial cell pyroptosis via modulation of Lin28b/let-7 pathway in atherosclerosis." (PMID 37497437, 2023). "It is notable that Sirt6 abrogates the increase in age-induced inflammatory cytokines related to atherosclerosis." (PMID 37497437, 2023). "Taken together, emerging evidence suggests that sirtuin isoforms, particularly SIRT1 and SIRT6, play a protective role against EC senescence and atherosclerosis." (PMID 37894840, 2023). "Taken together, Sirt6 should be deemed as playing a dichotomous role in modulating the pathophysiology of atherosclerosis." (PMID 37497437, 2023). "Sirt6 downregulates Lin28b expression and demonstrates anti-pyroptosis effect in the inflammatory progress of atherosclerosis." (PMID 37497437, 2023). "Latest research demonstrated that circular RNA circ_0026218 ameliorates atherosclerosis development through upregulation of Sirt6." (PMID 37497437, 2023). "Among the seven mammalian sirtuins (SIRT1–SIRT7), SIRT1 and SIRT6 have been widely studied in the context of EC senescence and atherosclerosis." (PMID 37894840, 2023). "Reconstitution of Sirt6 in atherosclerotic mice improved lipid metabolism disorder and prevented the progression of atherosclerosis." (PMID 37736721, 2023). "Since it is generally accepted that atherosclerosis is characterized as a set of chronic inflammatory responses, Sirt6 plays a significant role in regulating inflammation." (PMID 37497437, 2023). "Adipophilin and PLIN2 have been reported to correlate with atherosclerosis, their expression was compared among the plaques of ApoE−/−, ApoE−/−: Sirt6−/− and ApoE−/−: Sirt6Tg mice." (PMID 37736721, 2023).
atherosclerosis (continued). "SIRT6 (Sirtuin 6) is a nuclear deacetylase and plays a key role in regulating VSMCs senescence and atherosclerosis." (PMID 38031118, 2023). "Despite the widely accepted idea that Sirt6 is involved in the maintenance of glucose and lipid homeostasis, roles of Sirt6 in the onset and progression of atherosclerosis remains mysterious." (PMID 37497437, 2023). "SIRT6 is another well-documented sirtuin that can protect against EC senescence and atherosclerosis by promoting genomic stability, reducing inflammation, and epigenetically modulating age-related gene expression." (PMID 37894840, 2023). "The theory that Sirt6 prevents atherosclerosis by modulating lipid homeostasis has also been well delineated." (PMID 37497437, 2023). "We primarily examine the roles of Sirt6 in atherosclerosis, coronary heart disease, cardiac ischemia/reperfusion (I/R)-induced injury, diabetic cardiomyopathy, hypertension, cardiac hypertrophy, heart failure, cardiac fibrosis, and DM." (PMID 37497437, 2023). "Genetic overexpression of SIRT6 in VSMCs delayed senescence and inhibited atherosclerosis in HFD-fed ApoE-/- mice." (PMID 35855341, 2022). "Recent studies highlighted the pleiotropic protective actions of SIRT6 in angiogenesis and cardiovascular diseases, including atherosclerosis, hypertension, heart failure, and stroke." (PMID 35855341, 2022). "Overexpression of SIRT6 in VSMCs alleviated cellular senescence and inflammation both in vivo and in vitro, and inhibited the development of atherosclerosis in vivo." (PMID 35569818, 2022). "Here, we discuss recent advances in the understanding of SIRT6 in aging-related vascular diseases, including atherosclerosis, hypertension, and ischemic stroke." (PMID 35855341, 2022). "A follow-up study of bone marrow transplantation validated the important role of macrophage SIRT6 in preventing atherosclerosis in mice." (PMID 35855341, 2022). "SIRT6 has been proposed to play protective roles in atherosclerosis, mainly depending on three approaches, namely, decreasing LDL cholesterol, reducing macrophage foam cell formation, or preventing endothelial dysfunction." (PMID 35224092, 2022). "In contrast, ITCH ubiquitinates SIRT6, promoting its degradation, thereby disrupting FA metabolism and leading to hypercholesterolemia and hyperlipidemia and accelerating atherosclerosis progression." (PMID 36465178, 2022). "During HFD-induced insulin resistance in the liver, SIRT6 deficiency promoted M1 macrophage transformation and the inflammatory response, suggesting that SIRT6-mediated macrophage polarization contributes to its effects in atherosclerosis." (PMID 35855341, 2022). "There are seven mammalian sirtuins, with SIRT1 and SIRT6 investigated with regard to protection against atherosclerosis." (PMID 35569818, 2022). "Endothelial dysfunction is the initiation step in the development of atherosclerosis, indicating that SIRT6 participates in the early stages of the disease." (PMID 35855341, 2022). "Here, we will focus on the roles of SIRT6 in atherosclerosis (early events), cardiac hypertrophy and fibrosis (middle-stage events), heart failure (end-stage events) and I/R injury (recovery-stage events) in CVDs." (PMID 36465178, 2022). "Our findings revealed that SIRT6 in macrophages inhibited HFD-induced atherosclerosis in ApoE-/- mice by reducing the levels of H3K9ac and H3K56ac." (PMID 35855341, 2022). "Patients with diabetic atherosclerosis showed higher endothelial SIRT6 in plaques following administration of glucagon-like peptide-1 (GLP-1) receptor agonists, revealing endothelial SIRT6 as a curative effect index and target for atherosclerosis treatment." (PMID 35855341, 2022). "Several studies have demonstrated that knockdown of SIRT6 inhibited the development of atherosclerosis (AS), indicated SIRT6 as a protective factor for AS." (PMID 33436551, 2021).
atherosclerosis (continued). "This indicates that endogenous levels of SIRT6 is a critical regulator of VSMC senescence and reveals a therapeutic potential of SIRT6 in atherosclerosis." (PMID 33855020, 2021). "SIRT6 protein stability is positively regulated by the ubiquitin ligase CHIP (C terminus of HSC70-interacting protein) but their expression is reduced in atherosclerosis." (PMID 33353368, 2021). "We identify a novel and unrecognized role for SIRT6 in protecting VSMCs from senescence through prevention of telomere damage that requires its deacetylase function, highlighting the therapeutical potential of SIRT6 in atherosclerosis." (PMID 33353368, 2021). "Among all SIRTs, SIRT1 and SIRT6 are characterized for their protective mechanism against inflammation, vascular aging, and atherosclerosis in DM." (PMID 34071497, 2021). "Recent reports argued that the epigenetic regulation of NKG2D ligands is also involved in atherosclerosis of SIRT6 heterozygous mice." (PMID 33855020, 2021). "In summary, we describe a novel, important and unrecognized role for SIRT6 in VSMC senescence and atherosclerosis, and identify the ubiquitin ligase CHIP as a critical regulator of SIRT6 stability, whose expression is also reduced in VSMCs in atherosclerosis." (PMID 33353368, 2021). "SIRT6 gene knockout promotes the formation of macrophage foam cells, hence promoting the formation of atherosclerosis." (PMID 33855020, 2021). "Restoring SIRT6 in VSMCs reduces atherosclerosis, markers of cell senescence, and inflammation in vivo." (PMID 33353368, 2021). "SIRT6 has been revealed to be a negative regulator in endothelial dysfunction and atherosclerosis development." (PMID 34071497, 2021). "Our findings suggest a specific mechanism for SIRT6 downregulation in atherosclerosis, through fatty acid-induced reduction in CHIP and increased SIRT6 degradation." (PMID 33353368, 2021). "Generally, these findings suggest that SIRT6 plays a vital role in low-density lipoprotein cholesterol metabolism, potentially counteracting the formation of atherosclerosis." (PMID 33855020, 2021). "Given its distinct role in each of these processes, SIRT6 is an important target to study in VSMCs and in atherosclerosis." (PMID 33353368, 2021). "VSMC SIRT6 reduces atherosclerosis and markers of plaque cell senescence and preserves features of plaque stability in ApoE−/− mice, which is lost when VSMCs express SIRT6H133Y." (PMID 33353368, 2021). "Senescent VSMCs acquire a glycolytic and proinflammatory state that can also promote atherosclerosis, and which can be prevented by restoring SIRT6 levels." (PMID 33353368, 2021). "We also studied the effects of VSMC-specific overexpression of SIRT6 on atherosclerosis in mice and their dependence on its deacetylase activity." (PMID 33353368, 2021). "A previous publication using an ApoE-/- atherosclerotic animal model showed that SIRT6 mRNA and protein levels were downregulated in atherosclerotic aortas and that SIRT6 has a protective role against the development of atherosclerosis." (PMID 33171439, 2020). "Inflammation mediated by myeloid cells trigger receptors 1 (TREM-1) is important for atherosclerosis development, while sirtuin 6 (Sirt6) levels decrease in atheroscleoritc plaque." (PMID 30993014, 2019). "RNA-sequencing profiling revealed that SIRT6 overexpression decreased the expression of multiple atherosclerosis-related genes, including proatherogenic gene TNFSF4 (tumor necrosis factor superfamily member 4)." (PMID 27249230, 2016). "Sirt6 heterozygous mice show exacerbated atherosclerosis and exhibit feature of instable atherosclerotic plaques than wild-type mice." (PMID 27045575, 2016). "In summary, our study demonstrates that heterozygous Sirt6 mice have more severe atherosclerosis and exhibit feature of less stable atherosclerotic plaques, suggesting the protective roles of Sirt6 in atherosclerosis." (PMID 27045575, 2016).